IGHG3 (immunoglobulin heavy constant gamma 3 (G3m marker))
Diseases named in the same sentence as IGHG3 in open-access papers:
IGHG3 is named in the same sentence as 266 diseases in open-access papers, as found by Europe PMC text mining. Sharing a sentence is not in itself a finding about the gene and the disease. The quoted sentences say what the papers report.
malaria (197 papers, 2005 to 2026). Malaria is a serious and sometimes fatal disease caused by a parasite that commonly infects a certain type of mosquito which feeds on humans. "More information regarding IGHG3 polymorphism frequencies in endemic populations will help to clarify potential selective pressures on this SNP and its role in malaria clinical outcomes." (PMID 28991911, 2017).
COVID-19 (81 papers, 2020 to 2025). A disease caused by infection with severe acute respiratory syndrome coronavirus 2. "As a whole, COVID-19 patient PC GSVA scores were significantly correlated with IGHG3 and IGHA1 Ig heavy chain isotypes." (PMID 36189236, 2022). "In particular, four of the shared six genes between the McClain and Lee data were immunoglobulin encoding genes: IGHG1, IGHG3, IGHG4, and IGLC2, all of which were consistently upregulated in a COVID-19 specific manner across the datasets." (PMID 35991542, 2022). "We also investigated whether these GM alleles synergistically/epistatically with IGHG3 and FCGR2A alleles—which have been previously implicated in COVID-19—modulated the extent of COVID-19 severity." (PMID 38602517, 2024). "COVID-19 and IAV coexpressed genes might be associated with essential biological functions of B cells; for example, IGHG3 and IGLC2 were B cell marker genes." (PMID 37956172, 2023). "In COVID-19 cases, somatic hypermutation (SHM) and class-switch recombination (CSR) events of IGHG3 are more frequent than those of other IgG subclasses." (PMID 38238762, 2024). "Additional profiling of immune response-related genes highlighted the preferential proximal PAS usage of immunoglobulin genes, such as IGHM, IGHG1, IGHG3, and IGHA2, especially in B cells and plasma cells of COVID-19 samples." (PMID 34376223, 2021). "Our IPA analysis found that the IgG component genes, IGHG3, IGHG4, and IGHV3-30 are upregulated in the lungs of severe COVID-19 patients." (PMID 34899680, 2021). "Due to the pivotal role of IgG1 in response against SARS-CoV-2, we hypothesized that common functional variants in the IGHG1 gene—either individually or synergistically with IGHG3 and FCGR2A—might modulate the extent of COVID-19 severity." (PMID 38602517, 2024). "Specifically, signatures of plasma cells (IGHG3, IGKC, IGHM, JCHAIN, IGHG2, IGKV4-1, IGLV3-1, IGHA1), activated fibroblasts (COL1A1, COL1A2, COL3A1), inflammatory cytokines (CXCL9, CCL18) and complement factors (C1QB, C1QC) dominated the DE genes for the COVID-19 lung sections." (PMID 37858234, 2023).
viral infections (52 papers, 2013 to 2025). "Interestingly, the elevated IgG gene expression was mainly due to IgG1 (IGHG1) and IgG3 (IGHG3), but not IgG2 (IGHG2), which is in line with the presumed IgG1- and IgG3-switched phenotype of T-bet+ B cells both in MS and during viral infections." (PMID 36796230, 2023).
influenza (26 papers, 2010 to 2025). An acute viral infection of the respiratory tract, occurring in isolated cases, in epidemics, or in pandemics; it is caused by serologically different strains of viruses (influenzaviruses) designated A, B, and C, has a 3-day incubation period, and usually lasts for 3 to 10 days. "Influenza-specific IGHG sequences encoded IGHG1 and IGHG6 isotypes, consistent with reports of influenza-specific serum IgGa (encoded by IGHG1) but not IgGT (encoded by IGHG3 and IGHG5) in response to vaccination of adult horses." (PMID 28520789, 2017). "Reanalysis of prior PBMC RNA-seq data on influenza vaccine responses in younger adults showed upregulated expression of IGHG1 and IGHG3 at day 7, whereas pneumococcal vaccines upregulated the expression of IGHA2 and IGHG2." (PMID 38182669, 2024). "The use of a pan-IGHG reverse primer allowed amplification of any IgG isotypes, and sequence analysis revealed the use of IGHG1, IGHG3, and IGHG5 isotypes in foals, and IGHG1 and IGHG6 in mares for both KLH- and influenza-specific B cells." (PMID 28520789, 2017).
lupus (22 papers, 2012 to 2024). "Immunoglobulin gamma-3 chain C (IGHG3) levels have been detected in the blood and tissue of patients with systemic lupus erythematosus (SLE)." (PMID 37108090, 2023). "As laboratory markers, low C3 and anti-dsDNA antibody positivity indicate higher SLE activity, and leukopenia and lymphopenia indicate hematologic involvement of SLE, suggesting that serum IGHG3 levels are correlated with lupus activity." (PMID 37108090, 2023).
nephritis (8 papers, 2012 to 2024). Inflammation of renal tissue. "The measurement of urinary IGHG3 levels can help differentiate active nephritis." (PMID 37108090, 2023). "The salivary IGHG3 levels correlated with the erythrocyte sedimentation rate (r = 0.26, p = 0.01), anti-double-stranded DNA (dsDNA) antibody levels (r = 0.25, p = 0.01), and nephritis (r = 0.28, p = 0.01)." (PMID 33573068, 2021). "Notably, enhanced levels of IGHG3 have also been observed in the saliva, serum, and urine of SLE patients, and the measurement of IGHG3 levels in urine may aid in differentiating active nephritis." (PMID 39872521, 2024). "Urinary IGHG3 was higher in patients with nephritis than in those without (119.5 ± 110.0 vs. 49.8 ± 54.4 ng/mL; p < 0.01)." (PMID 37108090, 2023).
breast carcinoma (7 papers, 2015 to 2025). "Conversely, other reports describe IGHG1 and IGHG3 as suppressor genes in breast cancer recurrence." (PMID 41149858, 2025). "IGHG3 specifically has also been shown to be overexpressed in a number of cancers, again predominantly epithelial tumours, including non-squamous non-small cell lung cancer, breast cancer, prostate cancer, malignant mesothelioma and CRC." (PMID 36008952, 2022).
Arthritis (4 papers, 2015 to 2025). Inflammation of a joint. "Together, these findings suggest that relative levels of Ighg3/Ighm may be related to a basal rate of inflammatory-erosive activity explaining differences in arthritis at the same stage of disease." (PMID 37691918, 2023). "Interestingly, the Ighg3/Ighm association with talus bone volumes remained consistent regardless of Early vs Advanced arthritis." (PMID 37691918, 2023). "Further, we identified a novel relationship between Ighg3 expression and severity of erosive arthritis independent of disease stage, which may relate to the variation of arthritis progression within TNF-Tg cohorts at the same age." (PMID 37691918, 2023). "Given both Ighg2b/Ighm and Ighg3/Ighm showed significant negative correlations with talus bone volume, we performed a multiple linear regression to control for the effects of the differentially expressed immunoglobulins and the stage of arthritis (Early vs Advanced)." (PMID 37691918, 2023).
periodontitis (4 papers, 2014 to 2022). An acute or chronic inflammatory process that affects the tissues that surround and support the teeth. "In subjects with DL plus periodontitis versus HS, three DEG were confirmed (DAB2, CD47, and HLADRB4), and in the comparison between subjects with periodontitis alone versus HS: the IGHG3 gen (IGHDL-P) was upregulated, and the ITGB2 and HLADRB4 genes were downregulated." (PMID 36233348, 2022).
pulmonary TB (4 papers, 2015 to 2025). "All the proteins such as GGH, IGHG3 and HPT were closely related to the body’s metabolism, immune function and pulmonary TB." (PMID 26198726, 2015).
Stroke (4 papers, 2016 to 2026). Sudden impairment of blood flow to a part of the brain due to occlusion or rupture of an artery to the brain. "In the findings of this study, IGHG1 and IGHG3 are first determined in stroke patients’ platelets, these proteins may interact with platelets surface receptors." (PMID 27336623, 2016). "IGHG3, which is also involved in acute rejection, may contribute to platelet activation during ischemic stroke, and it is expected to be a potential target for the treatment of the early phase of stroke." (PMID 35745003, 2022).
lung carcinoma (3 papers, 2020 to 2022). "Several studies indicated that IGHG3 is overexpressed in multiple cancer types, such as prostate, breast, and lung cancers, which can differentiate tumor from normal tissues." (PMID 32039832, 2020). "Notably, elevated expression levels of production of immunoglobulin-related genes IGHG4, IGKC, IGLC2, IGHG3, and PLAU were detected in the SPP1-Mφ cluster, suggesting the proinflammatory and anti-tumor functions of this cluster in lung cancer." (PMID 36008393, 2022).
non-small cell lung carcinoma (3 papers, 2022 to 2025). A group of at least three distinct histological types of lung cancer, including non-small cell squamous cell carcinoma, adenocarcinoma, and large cell carcinoma. "In addition, elevated IGHG3 expression was observed in advanced non-small-cell lung cancer patients who responded to carboplatin plus paclitaxel chemotherapy compared with non-responders." (PMID 41149858, 2025).
hypothyroidism (2 papers, 2016 to 2024). Abnormally low levels of thyroid hormone. "Our study indicates that ISG15 can serve as a diagnostic biomarker for hyperthyroidism, ZNF683 can be considered as one of the diagnostic biomarkers for hypothyroidism, and elevated expression of IGHG3 suggests abnormal thyroid function in patients." (PMID 39872521, 2024). "Key signaling molecules were identified: ISG15 for hyperthyroidism, ZNF683 for hypothyroidism, and IGHG3 common to both conditions." (PMID 39872521, 2024). "Additionally, ELISA assays revealed that IGHG3 is extremely expressed in the serum of patients with hyperthyroidism and hypothyroidism." (PMID 39872521, 2024). "The expression levels of IGHG3, ISG15, and ZNF683 were analyzed in relation to clinical examination data from patients with hyperthyroidism, hypothyroidism, and healthy individuals." (PMID 39872521, 2024). "Through a combined analysis of gene transcriptomics and proteomics between the hypothyroidism group and healthy controls, we identified key differential genes ZNF683 and IGHG3 in the resulting network regulatory diagram." (PMID 39872521, 2024). "The consequences indicated that the serum content of IGHG3 were meaningfully higher in both AITD hyperthyroidism and hypothyroidism group patients contrapositive to the healthy controls and non-AITD patients." (PMID 39872521, 2024). "Using clinical baseline data collected from participants and ELISA results for IGHG3, ISG15, and ZNF683, we randomly divided the samples into training and testing groups to construct prediction models for patients with AITD hyperthyroidism and hypothyroidism." (PMID 39872521, 2024).
mild cognitive impairment (2 papers, 2020). "At variance, we observed a decrement of CLU, IGHG3, and LMW IGLC1 in A in comparison to Y and C. Among these proteins, CLU is known to enhance amyloid clearance and modulate neuroinflammation in mild cognitive impairment." (PMID 33260845, 2020).
osteosarcoma (2 papers, 2021 to 2023). A usually aggressive malignant bone-forming mesenchymal neoplasm, predominantly affecting adolescents and young adults. "A previous study revealed that gene PPARG, gene IGHG3, and gene PDK1 were correlated with osteosarcoma." (PMID 34188683, 2021). "In osteosarcoma tumor microenvironment-related literature, we take notice that the connection between the score of immunity and survival state has been investigated, and C3AR1, PPARG, PDK1, IGHG3, and C1Q are recognized as prognostic biomarkers." (PMID 36844870, 2023).
Splenomegaly (2 papers, 2004 to 2025). Abnormal increased size of the spleen. "However, unlike in Lyn-/-IL-10-/- mice, there was no enhancement of splenomegaly, CD4+ T cell activation (as measured by CD69 expression), CD4 T cell naïve and effector memory frequencies, or myeloid expansion in Lyn-/-.Ighg3-cre.DTA and Lyn-/-.Ighg3-cre.IRF4f/f mice compared to Lyn-/- controls." (PMID 41445737, 2025).
Cachexia (1 paper, 2022). Severe weight loss, wasting of muscle, loss of appetite, and general debility related to a chronic disease. "B cells from patients with cachexia showed lower expression of MHC-II molecules (HLA-DRB5, HLA-DQA2) and higher expression of the immunoglobulins (IGHG2, IGHG3, IGKC), and genes involved in BCR signaling." (PMID 36376273, 2022).
cervical cancer (1 paper, 2014). A primary or metastatic malignant neoplasm involving the cervix. "It should be pointed that we selected IGHG1 for the silencing target only rather than IGHG2, IGHG3 and so on because knockdown of endogenous IGHG1 could lead to more significant biological effects than that of others in cervical cancer cells according to our preliminary experiments." (PMID 25179302, 2014).
Mycobacterium infection (1 paper, 2015). Infections with bacteria of the genus Mycobacterium. "GGH was associated with folate metabolism in PYD cases, IGHG3 was linked to the control of Mycobacterium infection in HFYD patients, and HPT was involved in hypoxia in DQY patients." (PMID 26198726, 2015). "GGH was associated with folate metabolism in PYD patients, and IGHG3 was linked to the control of Mycobacterium infection in HFYD patients." (PMID 26198726, 2015). "The current results suggested that IGHG3 may be associated with the control of Mycobacterium infection in HFYD patients." (PMID 26198726, 2015).
infection (265 papers, 2006 to 2025). The state of being infected such as from the introduction of a foreign agent such as serum, vaccine, antigenic substance or organism. "In plasma cells, PCV2 infection reduced the expression of Igha, upregulated the expression of Ighm, and did not significantly affect the expression of Ighd, Ighg1, Ighg2b, and Ighg3." (PMID 41011514, 2025). "infections were observed in children with the IGHG3*30 allele compared to children without the allele (β= -1.736, 95% CI [-3.39, -0.079], p=0.038)." (PMID 40717585, 2025). "IGHG3 could bind with IgG Fc receptor (FcγR) of neutrophilic granulocyte and macrophages, thereby promoting phagocytosis and controlling the infection." (PMID 26198726, 2015). "Elevated serum IGHG3, on the one hand could combine with FcγR, mediate the macrophage phagocytosis, and control the infection." (PMID 26198726, 2015). "An increased expression of IGHG1, IGHG2, IGHG3, IGLV3-21, and IGLV6-57 was noted during active infection at 0 weeks compared with that at 8 weeks." (PMID 37434783, 2023). "We reported a high expression of IGHG family (IGHG1, IGHG2, and IGHG3) and IGLV family (IGLV3-21 and IGLV6-57) at 0 weeks, which are clinically correlate with active infection." (PMID 37434783, 2023). "Germline transcription of Ighg1, Ighg3, Ighg2b, and Ighg2a/c was greatly enhanced in CD5- B-1b cells from A/J compared to C57BL/6J mice on day 5 of secondary infection, suggesting heightened isotype class switching occurred in mice in the resistant background." (PMID 34871323, 2021).
tumor (62 papers, 2011 to 2026). "From the cell ratio, it can be seen that Monocytes_IGHG3 is only present in cancer tissues, Monocytes_APOE is also abundant in tumor tissues, and Monocytes_STMN1 is more distributed in healthy tissues." (PMID 36569220, 2022). "Several publications indicated that IGHG3 can be overexpressed in many different cancer cells and can differentiate tumor from normal." (PMID 23977302, 2013). "The tumor-associated proteins identified in study, PDIA6, MEG3, SDCCAG3, IGHG1 and IGHG3 have been previously reported to have cancer-associated properties." (PMID 23977302, 2013). "We found IGHG1 and IGHG3 were significantly enriched in Myeloid Predominant compared to Immune Neutral and Immune Desert (two-sided Student’s t test, p = 0.03 and 0.008), suggesting that potential antibody-producing cells infiltrated these tumours." (PMID 37679810, 2023). "Using an independent dataset (TCGA-COAD) The Cancer Genome Atlas (TCGA) Colon Adenomarcinoma (COAD) dataset which annotates 571 CRC patient samples by RNA-sequencing, we did not observe a unique sub-population of CRC patients with elevated IGHG3 expression in their tumours." (PMID 36008952, 2022). "Various genes that were significantly changed, such as CD79B, CLDN2, SPP1 and IGHG3 were the marker genes of the identified cell types or sub-populations, probably owing to the high heterogeneity in cellular compositions across the tumor samples, as observed above." (PMID 37488117, 2023). "Regardless of the important role of IgG1/IgG3 isotypes in initiating tumor-specific antibody-dependent cellular cytotoxicity (ADCC), high IGHG3/1 class switch events were a neutral survival parameter in ESCC." (PMID 35812448, 2022). "T-C7 was scattered around T-C6 and was relatively high in immunoglobulins such as IGHG3 (immunoglobulin heavy constant gamma 3 involved in B-cell activation) and IGKC (immunoglobulin kappa constant), which are markers secreted by tumor-infiltrating B cells." (PMID 37124494, 2023). "We then analyzed and marked the top 20 DEG genes in tumor core regions and found that IGHG1, IGHG3, IGHG4, IGKC, and IGLC2 (effector markers for humoral immunity) were notably downregulated in core regions, possibly indicating an immunosuppressive microenvironment (ISME)." (PMID 35673582, 2022). "Indeed, IgG3 levels in the CRC patient sera were elevated compared with normal donors, again suggesting that the antibody response to IGHG3 products was to infiltrating B cells and/or antibodies rather than IGHG3 production within the tumour cells." (PMID 36008952, 2022). "Indeed, as examples, the high expressions of fibroblasts, myofibroblast markers (COL1A1, COL1A2), and B cell markers (IGLC3, IGHG3) were found in our LMD-isolated stroma samples and TCGA tumor samples, but not in our LMD-isolated tumor parts." (PMID 33916417, 2021).
cancer (25 papers, 2011 to 2025). A tumor composed of atypical neoplastic, often pleomorphic cells that invade other tissues. "The biological functions of IGHG1 and IGHG3 expression in cancer cells remains unclear despite some reports showing that IgG secreted by cancer cells had some unidentified capacity to promote the growth and survival of cancer cells." (PMID 23977302, 2013). "CCL15 was also increased as the pseudo-time progressed and was dominant in the end stages of the pseudo-time axis; Conversely, other key molecules such as IGHG1, IGHG3, IGHG4, IGKC, IGLC2 decreased gradually among all the carcinoma sectors in HCC1 and HCC4." (PMID 35673582, 2022).
neurological disorders (2 papers, 2023 to 2025). "Elevated levels of IGHG3 and IGKC, components of IgG molecules, suggest ongoing humoral immune responses in the CNS, aiding in the distinction of MS from other neurological disorders." (PMID 40649948, 2025).
IGHG3 also shares sentences with these, for which no sentence is quoted: parasitemia (20 papers); Allergy (15); Autoimmunity (15); HIV-1 infection (14); autoimmune disease (13); bacterial infections (13); infectious disease (11); glomerulonephritis (10); schistosomiasis (10); tetanus (10); antibody deficiency (9); dengue (9); Immunodeficiency (9); leprosy (8); co-infection (7); myasthenia gravis (7); pertussis (7); pneumonia (7); renal disease (7); Respiratory tract infection (7); ZIKV infection (7); Hepatosplenomegaly (6); lupus nephritis (6); melanoma (6); onchocerciasis (6); anemia (5); asthma (5); Crohn disease (5); falciparum malaria (5); respiratory infections (5).
A further 212 diseases each share a sentence with IGHG3 in 4 papers or fewer.